HSF2 (heat shock transcription factor 2)
Diseases named in the same sentence as HSF2 in open-access papers (continued):
Sharing a sentence is not in itself a finding about the gene and the disease.
glioma (4 papers, 2011 to 2021). A benign or malignant brain and spinal cord tumor that arises from glial cells (astrocytes, oligodendrocytes, ependymal cells). "Colligin 2 was higher expression in glioma neovasculature, which compared to the normal vasculature of the brain, was associated with overexpression of HSF2 in glioma neovasculature." (PMID 26078353, 2015). "The expression levels of TUG1, miR-144 and HSF2 in human glioma vascular endothelial cells and normal brain vascular endothelial cells were detected by quantitative real-time PCR." (PMID 26078353, 2015). "We observed that HSF2 was highly expressed in glioma endothelial cells (GEC) from glioma tissues, which was consistent with the following literature." (PMID 26078353, 2015). "In the present study, the major aim was to investigate the expression of lncRNA-TUG1, microRNA-144 and transcription factors HSF2 in glioma microvascular endothelial cells." (PMID 26078353, 2015). "The potential involvement of HSF2 in glioma is interesting considering that HSF2 is involved in central nervous system development." (PMID 24212658, 2011). "Furthermore, the expression levels of HSF2 were significantly up-regulated in low or high-grade glioma group compared with that in the normal brain tissue group." (PMID 26078353, 2015). "In addition, the expression levels of HSF2 in high-grade glioma group was higher than that in the low-grade glioma group (P < 0.01)." (PMID 26078353, 2015). "HSF2 has been reported could be activated by high extracellular potassium and was involved in the up-regulation of alphaB-crystallin gene expression in human glioma U-251MG cells." (PMID 26078353, 2015).
Hypertension (4 papers, 2017 to 2025). The presence of chronic increased pressure in the systemic arterial system. "Isolated adult human whole heart tissue showed MEL18-mediated HSF2-IGF-IIR pathway is upregulated in hypertension human heart, compared to health human heart." (PMID 29270451, 2018).
male infertility (4 papers, 2020 to 2024). The inability of the male to effect fertilization of an ovum after a specified period of unprotected intercourse. "The research of Gui and his colleagues showed that the HSF2 mutation causes male infertility for the first time." (PMID 36430241, 2022). "The HSF2 gene mutation discovered to cause male infertility for the first time is loss-of-function mutation." (PMID 36430241, 2022). "Our study could advance the association between the expression profile of HSF2 and the male sterility of the cattle-yak, and accelerate the analysis of the molecular underlying mechanism of male infertility in the cattle-yak." (PMID 38791628, 2024). "Thus, a representative analysis of variants/mutations of HSF1, HSF2 andUBE2I genes in multiple cohorts along with their functional assay will provide insights into the cause of male infertility." (PMID 35540693, 2021). "A single study on HSF2 gene in this context is known.Therefore, it is of interest to document data on the link between male infertility and HSF1, HSF2 and UBE2I gene polymorphisms." (PMID 35540693, 2021). "Overall, our data first noted that the attenuated expression of HSF2 in cattle-yak testes may be the latent origin of meiotic arrest, which could induce male infertility in cattle-yak." (PMID 38791628, 2024). "Thus, although previous studies have demonstrated that the HSF1 and HSF2 genes are indispensable for spermatogenesis, their functional insights into genotype sequencing and male infertility are still inconsistent." (PMID 38791628, 2024). "Taken together, our data has been confirmed repeatedly that the differential expression of the HSF2 gene in the cattle-yak may be the potential factor of male infertility, and the specific regulatory mechanism still needs further analysis." (PMID 38791628, 2024). "On the basis of the genotypic analysis of our findings, we could not find any relationship between rs78202224 (C>A),rs139496713 (C>T) and rs45504694 (C>A) SNPs in HSF1 and HSF2 genes and male infertility." (PMID 35540693, 2021).
Azoospermia (3 papers, 2020 to 2024). Absence of any measurable level of sperm,whereby spermatozoa cannot be observed even after centrifugation of the semen pellet. "Similarly, a previous study revealed that in humans, the R502H mutation of HSF2 would contribute to the onset of male fertility potential and the process of meiosis of spermatogenic cells, leading to idiopathic azoospermia (IA) in males." (PMID 38791628, 2024). "Importantly, the accumulating evidence suggests that a significant number of coding mutations in the exons of HSF2 were found in idiopathic azoospermia (IA) patients, indicating HSF2 played a crucial role in human spermatogenesis via regulating the cell cycle and apoptosis." (PMID 38791628, 2024). "Furthermore, the available data suggest that the HSF2 gene accounts for spermatogenesis by regulating the cell cycle in human; thus, the misregulation of the HSF2 gene may cause an increased risk of idiopathic azoospermia (IA)." (PMID 38791628, 2024). "Specifically, the HSF family members, HSF1 and HSF2, are likely to play important roles in human spermatogenesis as some azoospermia patients harbor deletion of HSFY on AZFb." (PMID 33318309, 2020). "Likewise, it was also reported that mutations in the HSF2 gene were associated with non-obstructive azoospermia (NOA) in humans." (PMID 38791628, 2024).
colitis (3 papers, 2021 to 2022). Inflammation of the colon. "In this study, a DSS (dextran sulfate sodium)-induced colitis model of hsf2-deficient mice was used to explore the relationship between HSF2 and apoptosis in IECs." (PMID 36430241, 2022). "Compared with wild-type mice, the level of ROS in intestinal mucosa of hsf2−/− colitis mice was significantly increased." (PMID 35860016, 2022). "As reported, mitophagy can regulate the activation of NLRP3 inflammasome in the intestinal mucosa of mice with DSS-induced colitis and play a protective role, which is similar to the role of HSF2 in UC." (PMID 35860016, 2022). "DSS was used to induce colitis in hsf2−/−mice and wild-type mice." (PMID 35860016, 2022).
colorectal cancer (3 papers, 2018 to 2024). A primary or metastatic malignant neoplasm that affects the colon or rectum. "The results directly demonstrated the involvement of HSF2 in colorectal cancer, renal cell carcinoma, hepatocellular carcinoma, endometrial cancer, small cell lung cancer, chronic myeloid leukemia, and viral carcinogenesis." (PMID 35087869, 2021).
hepatocellular carcinoma (3 papers, 2021 to 2025). A malignant tumor that arises from hepatocytes. "In not only hepatocellular carcinoma but also other carcinomas, HSF2 controls a few or several pathways at the same time and helps tumor growth." (PMID 36430241, 2022). "Koman and his colleagues reported that HSF2 is a novel target of Wnt/β-catenin/TCF (T cell factor) signaling in hepatocellular carcinoma." (PMID 36430241, 2022). "To date, several mechanisms for how HSF2 affects the characteristics of hepatocellular carcinoma have been suggested." (PMID 36430241, 2022). "Meng and his colleagues reported that HSF2 regulate aerobic glycolysis in hepatocellular carcinoma through the suppression of fructose-1,6-biphosphatase 1 (FBP1)." (PMID 36430241, 2022). "Additionally, HSF2 expression was higher in hepatocellular carcinoma tissues than in para-cancerous tissues, and the HSF2 expression level increased with tumor stage." (PMID 36430241, 2022). "Before their report in 2016, only one paper by Koman and his colleagues suggested that HSF2 may be positively involved in carcinogenesis using hepatocellular carcinoma." (PMID 36430241, 2022). "Recently, Guo and his colleagues showed that high expression of DNAJC24 (HSP40 Member C24, a heat shock protein) occurs in hepatocellular carcinoma patients with shortened life span and that the transcription of DNAJC24 is regulated by HSF2." (PMID 36430241, 2022). "As described, one of them is that HSF2 contributes to the hepatocellular carcinoma survival as a part of the Wnt/β-catenin/TCF pathway, and the other one is that HSF2 suppresses FBP1 and upregulates aerobic glycolysis essential for hepatocellular carcinoma growth." (PMID 36430241, 2022).
thyroid carcinoma (3 papers, 2021 to 2022). "Bioinformatics analysis of RNA-sequencing data suggested that HSF2 may be associated with the development of thyroid carcinoma by regulating SERPINA1 and FOSB expression." (PMID 34917120, 2021). "Through this analysis, they thought that HSF2 is involved in thyroid carcinoma development by regulating SERPINA1 and FosB genes." (PMID 36430241, 2022). "Zhang and his colleagues showed that HSF2 regulates FosB in thyroid carcinoma development." (PMID 36430241, 2022). "Bioinformatics analysis has demonstrated that HSF2 may be involved in the oncogenesis of thyroid carcinoma by mediating the expression of SERPINA1 and FOSB." (PMID 35087869, 2021).
hepatitis B (2 papers, 2021). "Notably, our GSEA and KEGG results suggested that HSF2 was also involved in many immunity-associated pathways (IL−17 signaling pathway and the adaptive immune system) and various microbial infections (hepatitis B, shigellosis, Yersinia infection, and herpes simplex virus 1 infection)." (PMID 35087869, 2021).
Huntington disease (2 papers, 2021 to 2022). Huntington disease (HD) is a rare neurodegenerative disorder of the central nervous system characterized by unwanted choreatic movements, behavioral and psychiatric disturbances and dementia. "In addition, in Huntington’s disease model (HD) mice, WT-HD, HSF2-hetero-HD, and HSF2-KO-HD mice showed different life spans." (PMID 36430241, 2022). "Our previous study demonstrated that HSF2 deficiency accelerated disease progression and shortened lifespan in a mouse model of Huntington’s disease, suggesting that HSF2 could be a potential therapeutic target for neurodegenerative diseases by regulating the expression of αB-crystallin (CRYAB)." (PMID 35087869, 2021).
melanoma (2 papers, 2023 to 2024). A malignant, usually aggressive tumor composed of atypical, neoplastic melanocytes. "This study describes the multi-level analysis of a model neoAg from the B16F10 murine melanoma, H2-Db/Hsf2 p.K72N68-76, as well as its cognate TCR 47BE7." (PMID 38459027, 2024). "Here, the authors describe a molecular mechanism by which the neoantigen Hsf2 p.K72N is recognised by a corresponding high affinity Hsf2 p.K72N-reactive T cell receptor, 47BE7, from the mouse melanoma line B16F10." (PMID 38459027, 2024). "Collectively, we determined the molecular mechanism of immunogenicity for the H2-Db-restricted B16F10 melanoma neoAg Hsf2 p.K72N68-76." (PMID 38459027, 2024). "Discovery of a fully validated neoantigen Hsf2 in melanoma B16 opens the opportunity to study the role of neoantigens in immunity of melanoma, including resistance to checkpoint blockade." (PMID 37507765, 2023). "Hsf2 was the only melanoma B16 neoantigen that passed validation." (PMID 37507765, 2023).
prostate adenocarcinoma (2 papers, 2021 to 2023). "HSP90AA1 gene expression was not significantly correlated with the gene expression of HSF1, HSF2, and HSF5 in prostate adenocarcinoma specimens." (PMID 36982267, 2023).
protein misfolding diseases (2 papers, 2014 to 2021). "In contrast to studies on HSF1, most studies on HSF2 have focused on protein misfolding diseases, aging, and the development of the embryo and sperm." (PMID 34917120, 2021).
alcohol abuse (1 paper, 2021). The use of alcoholic beverages to excess, either on individual occasions ("binge drinking") or as a regular practice. "Moreover, high HSF2 expression was related to poor OS and PFS rates in patients, regardless of race (white and Asian), sex, alcohol abuse, and hepatitis viral infection." (PMID 34917120, 2021).
fibrolamellar carcinoma (1 paper, 2021). "After stratification based on histological subtypes, HSF2 was expressed at higher levels in HCC, fibrolamellar carcinoma and hepatocholangiocarcinoma than in normal controls." (PMID 34917120, 2021).
gastric adenocarcinoma (1 paper, 2025). "This suggests that HSF2 modulates EBV gene expression in gastric adenocarcinoma cells, which is consistent with our findings in KSHV-infected cells." (PMID 40245053, 2025). "Similarly, HSF2 positively regulates EBV gene expression and intracellular viral genome copies in EBVaGC organoids and EBV-infected gastric adenocarcinoma cell lines." (PMID 40245053, 2025).
gastric cancer (1 paper, 2025). A primary or metastatic malignant neoplasm involving the stomach. "Due to its recently discovered role as causal agent of a molecular subtype of gastric cancer, we decided to test the effect of HSF2 in EBV life cycle using EBV-associated gastric cancer primary cells obtained from patient-derived- xenografts (PDXs)." (PMID 40245053, 2025). "In conclusion, these results indicated that HSF2 regulates EBV gene expression and viral genome copies in gastric cancer cells." (PMID 40245053, 2025). "In lymphatic endothelial cells infected with KSHV and in gastric cancer cells positive for EBV, ectopic HSF2 enhances the expression of lytic genes; While knocking down HSF2 significantly decreases their expression." (PMID 40245053, 2025). "HSF2 modulates viral gene expression in physiologically relevant models of viral-mediated oncogenesis, including primary KLEC and EBV-positive, patient-derived gastric cancer organoids." (PMID 40245053, 2025).
liver cancer (1 paper, 2021). An epithelial or non-epithelial malignant neoplasm that arises from the liver. "HSF2 protein expression was significantly upregulated in liver cancer tissues compared with normal liver tissues." (PMID 34917120, 2021).
liver diseases (1 paper, 2023). "In this regard, the role of HSF2BP in other liver diseases, and whether there is a mechanism independent of HSF2, warrant investigation." (PMID 36964632, 2023).
neuroblastoma (1 paper, 2019). Neuroblastoma (NB) is the most common solid, extracranial childhood tumor. "The co-transfection results in human neuroblastoma SK-N-AS cells showed that the overexpressed HSF2 decreased the ZNF804A transcription level, and its inhibition effect on the T allele was stronger than on the C allele." (PMID 30670685, 2019).
osteosarcoma (1 paper, 2025). A usually aggressive malignant bone-forming mesenchymal neoplasm, predominantly affecting adolescents and young adults. "In U2OS osteosarcoma cells stably infected with KSHV, where a less robust HSF1 depletion was obtained, we confirmed that HSF2 overexpression increased ORF50 levels regardless of HSF1 silencing." (PMID 40245053, 2025).
Sepsis (1 paper, 2016). Sepsis is defined as life-threatening organ dysfunction caused by a dysregulated host response to infection. "Other examples of such eQTL included HSF2, which encodes heat shock transcription factor 2, which is crucial to regulation of the heat shock response in infection, inflammation, and oxidative stress and has evidence of association with mortality in sepsis." (PMID 26917434, 2016).
spinocerebellar ataxia (1 paper, 2021). "Consistent with our previous studies, the results of the present study strengthen the important role of HSF2 in neurodegenerative diseases, including spinocerebellar ataxia." (PMID 35087869, 2021).
varicocele (1 paper, 2024). A condition characterized by the dilated tortuous veins of the spermatic cord with a marked left-sided predominance. "It was demonstrated that HSF2 gene-deficient male mice exhibited an increase in the vacuolization of the varicocele and an increase in apoptotic cells through disrupting the meiosis process in the spermatogonia and spermatogenesis, which was consistent with our findings in the cattle-yak." (PMID 38791628, 2024).
cancer (23 papers, 2009 to 2025). A tumor composed of atypical neoplastic, often pleomorphic cells that invade other tissues. "Because immune-infiltrating cells play an important role in cancer initiation and development, we then estimated the association between HSF2 expression and the infiltration levels of six major immune cells in 32 types of cancers." (PMID 35087869, 2021). "HSF2 expression was associated with poor DSS in three types of cancer, including KIRP, LIHC, and UCEC." (PMID 35087869, 2021). "Actually, loss of either HSF1 or HSF2 in cell experiments showed that these cells result in a dysregulated response to nutrient stresses in vitro and that tumor progression was reduced in cancer cell line xenografts." (PMID 36430241, 2022). "HSF2 was abnormally expressed in 25 out of 33 human cancers in datasets from the cancer genome atlas program, but was linked to either favorable or poor overall survival depending on the cancer type." (PMID 40457168, 2025). "HSF1 and HSF2 are also important contributors in devastating human pathologies like cancer, neurodegenerative disorders, and neurodevelopmental disorders." (PMID 40318841, 2025). "The evidence that increased expression of both HSF1 and HSF2 have critically important roles in cancer development and progression has been accumulating year after year." (PMID 36430241, 2022). "This is in line with a recent finding demonstrating that HSF2 occupies the same target genes with HSF1 in cancer to drive malignancy." (PMID 35687139, 2022). "We describe the short history in which HSF1 has been recognized to have strong and positive involvement in cancer before discussing novel discoveries in HSF2 and cancer relationship." (PMID 36430241, 2022). "If similar results are obtained using HSF2+/+ and HSF2−/− mice, the research on HSF2 in cancer will attract the attention of many more scientists." (PMID 36430241, 2022). "In this paper, we already described (see Section 5.3), they finally suggested that HSF2 as a critical cofactor of HSF1 in driving a cancer cell transcriptional program to support the anabolic malignant state." (PMID 36430241, 2022). "As the decrease in miR-202 can directly upregulate HSF2, HSF2-miR-202 pathway will exist in various cancers and carcinogenesis." (PMID 36430241, 2022). "The relationship between HSF2 and cancer was reported in 2010 for the first time, but rapidly increased in the last 5–6 years." (PMID 36430241, 2022). "We mainly referred to eight cancers by making one part for one kind of cancer, but in addition, some papers report that HSF2 also has a relationship with (muscle invasive) bladder cancer and cervical cancer." (PMID 36430241, 2022). "We will need to search chemicals modulating the function or expression of HSF2 and find that a few best ones and test them in cancer therapy as soon as possible." (PMID 36430241, 2022). "The first paper to indicate that HSF2 has some role in cancer is probably the report by Phillips and his colleagues." (PMID 36430241, 2022). "For example, the roles of HSF2 in nervous system protection, inflammation, maintenance of mitosis and meiosis, and cancer cell survival and death have been gradually unveiled." (PMID 36430241, 2022). "Under this circumstance, Mendillo and his colleagues tried to acquire more information about the relationship between HSF1 and HSF2 in cancer." (PMID 36430241, 2022). "Their report strongly indicates that the role of HSF2 in cancer biology is far greater than previously appreciated." (PMID 36430241, 2022). "The present study integrated existing data to explore the potential function of HSF2 in cancers and provides insights for targeting HSF2 to improve the therapeutic efficacy of immunotherapy." (PMID 35087869, 2021). "After stratification according to individual cancer stages, an increase in HSF2 expression was found in patients with stage 1, 2, 3 and 4 HCC compared to normal controls." (PMID 34917120, 2021).